OGT (O-linked N-acetylglucosamine (GlcNAc) transferase)
Diseases named in the same sentence as OGT in open-access papers (continued):
Sharing a sentence is not in itself a finding about the gene and the disease.
breast carcinoma (continued). "In addition, Ac-5SGlcNAc, an OGT inhibitor that decreased global O-GlcNAcylation, but not N-glycosylation or N-glycosylation, suppresses the proliferation of pancreatic and breast cancer cells." (PMID 33194731, 2020). "Reciprocally, OGT silencing or inhibition increases phosphorylation of AMPK, decreases phosphorylation of mTOR downstream effectors 4E-BP1 and p70S6K, decreases HIF-1a, GLUT1, and LDHA expression and impairs glucose uptake and growth in breast cancer cell lines." (PMID 30356686, 2018). "However, it is not known if certain breast cancer subtypes are more dependent on protein O-GlcNAcylation or whether inhibition of OGT could be a useful therapeutic opportunity for some of the patients." (PMID 30952976, 2019). "Manipulation of OGT and OGA activities in breast cancer cells showed that overexpression of OGT enhanced the migration/invasion of breast cancer cells in vitro and lung metastasis in vivo, but did not affect cell proliferation." (PMID 25426101, 2014). "If this feed-forward pathway for hyperglycemia-driven OGT activation is true, it might be applied to explain higher levels of OGT expression in other forms of cancer, including other non-TNBC subtypes of breast cancer, though we have not yet pursued this avenue of inquiry." (PMID 37231419, 2023).
diabetes (42 papers, 2011 to 2026). "Stabilization of PGC-1α and increased hepatic gluconeogenesis are associated with diabetes, and knocking down OGT and HCF-1 in the liver of diabetic mice helped reduce gluconeogenesis and regulate glucose homeostasis." (PMID 41602827, 2026). "As a result, this study aims to identify disease-causing and deleterious SNPs within the OGT gene and druggable targets to discover therapeutic drugs for diabetes mellitus via this gene." (PMID 38539217, 2024). "Future work focusing on studying the relationship between the conditional knockout of OGT and cilium length in neurons will aid us in better understanding the mechanisms of ciliopathy-associated obesity and diabetes." (PMID 37296641, 2023). "Previous work showed that OGT is highly expressed in the pancreas, and we demonstrated that hypo-O-GlcNAcylation in β-cells cause severe diabetes in mice." (PMID 36387851, 2022). "OGT is implicated in many human diseases including diabetes, cancer, and X-linked intellectual disability." (PMID 36383567, 2022). "Higher levels of OGT in adipose tissue are also linked to pro-inflammatory signaling in diabetes and hyperleptinemia, again illustrating the role OGT plays in regulating immune cells in adipose tissue." (PMID 33986724, 2021). "Deletion of OGT in β-cells causes glucose intolerance and overt diabetes at 6 weeks of age due to a significant loss of β-cell mass and insulin secretion dysfunction in vivo." (PMID 33460647, 2021). "Loss of CPE activity and proinsulin processing is also present in several mouse models of diabetes including those due to loss of mTORC1 signaling and deletion of OGT." (PMID 33457426, 2020). "Alzheimer's disease, diabetes, and several types of cancers have been linked to abnormal levels or behavior of O-GlcNAc, OGT, and OGA." (PMID 30237786, 2018). "These increases in O-GlcNAcylation levels are concomitant with changes in OGT/OGA activity, and, interestingly, diabetes is associated with a sarcomeric re-localization of OGT and OGA." (PMID 30420836, 2018). "Co-immunoprecipitation of OGT showed that diabetes reduced the OGT:HDAC2 association (P < 0.05), but this difference was removed by exercise training." (PMID 23835259, 2013). "Additional support for an association between protein O-glycosylation and diabetes comes from studies in which over-expression of OGT in muscle and adipose tissue caused diabetes in transgenic mouse models." (PMID 23554695, 2011). "OGT gene has emerged as the candidate gene associated with diabetes mellitus." (PMID 38539217, 2024). "Due to their potential effects on protein structure and function and, eventually, cellular processes involved in glucose metabolism and insulin signalling, deleterious single nucleotide polymorphisms (SNPs) in the OGT gene may have a major impact on diabetes." (PMID 38539217, 2024). "The OGT protein has been linked to the progression of diabetes mellitus because it catalyses the addition of the o-GlcNAc sugar moiety on nucleocytoplasmic proteins, a substrate of the hexosamine biosynthesis pathway, increasing the amount of intracellular glucose content." (PMID 38539217, 2024). "Interestingly, much like mutations in OGT, some of the most pronounced clinical manifestations of maternal pregestational diabetes mellitus during development affect the central nervous system, including neural tube defects and autism." (PMID 36924340, 2023). "This study not only delineates a previously unrecognized mechanism but also identifies the OGT/MAGI1 axis as a potential therapeutic target for preventing vascular complications in diabetes." (PMID 41546072, 2026). "Alterations in OGT have been found to be related to many pathologies, such as diabetes, cardiovascular disease, neurodegeneration and cancer." (PMID 38443583, 2024). "Under diabetes, the glucose absorption and/or OGT modification capacity was saturated, which implied that it was nearly impossible to further improve the modification ability." (PMID 38139429, 2023).
diabetes (continued). "Together, these data further support the concept that the athero-protective phenotype of SMC-specific OGT deletion is specific to only high glucose conditions, relevant to diabetes." (PMID 37175604, 2023). "Collectively, the current work underscores a direct regulatory role of SMC-derived OGT in lesion pathogenesis in diabetes." (PMID 37175604, 2023). "PIP3 recruits OGT to the cytomembrane through the strong interaction with the PPO domain of OGT under diabetes or another insulin-insensitive state." (PMID 35681484, 2022). "In pancreatic β-cells, deletion of OGT, a model of hypo-O-GlcNacylation, led to the development of diabetes in mice with deficits in both β-cell mass and function." (PMID 36387851, 2022). "Our group has recently shown that OGT plays an important role in β-cell health, and ablation of OGT in β-cells leads to diabetes and cell failure." (PMID 33460647, 2021). "Protein abundance of OGT tended to be increased overall by diabetes (P = 0.072) and was also increased at 16 weeks of diabetes on post hoc analysis (P < 0.05)." (PMID 32153425, 2020). "OGT is highly expressed in pancreatic islets, and perturbations to β-cell O-GlcNAcylation through OGT deletion or OGA inhibition cause β-cell failure and diabetes." (PMID 33457426, 2020). "To gain further insight into the contribution of OGT-mediated regulation of lipolysis to human health, we obtained human phenotypic data, including body mass index (BMI) and diagnosis of diabetes from the dbGAP database." (PMID 31924761, 2020). "In murine β-cells, reducing O-GlcNAcylation through deletion of OGT contributes to ER stress-induced apoptosis that prompts diabetes, while concomitant ablation of CHOP in these mice delays the progression of hyperglycemia." (PMID 33457426, 2020). "Conclusion: miR-200a/200b are involved in modulating HG-induced endothelial inflammation by regulating OGT-mediated protein O-GlcNAcylation, suggesting the therapeutic role of miR-200a/200b on vascular complications in diabetes." (PMID 29720943, 2018). "On the other hand, O-GlcNAcylation as typically seen in diabetes leads to altered mitochondrial protein O-GlcNAcylation, mislocalization of mitochondrial OGT and consecutively plays a role in mitochondrial dysfunction in the myocardium of diabetic rats." (PMID 27557097, 2016). "In one study, the authors evaluated the potential of OGT derived O-β-GlcNAc modifications on FoxO1 protein in diabetes." (PMID 22489133, 2012). "This was demonstrated in the context of insulin resistance in diabetes, where the O-GlcNAc transferase (OGT) and host cell factor-1 (HCF-1) interact with PGC-1α to promote its O-GlcNAcylation, facilitating BAP1 recruitment for deubiquitination and protecting PGC-1α from degradation." (PMID 41602827, 2026). "In addition, EPs inhibited the elevated expression of O-GlcNAc transferase (OGT) induced by diabetes, suggesting that EPs act similarly to an OGT inhibitor and contributed to mitigate hyperglycaemia." (PMID 39590803, 2024). "Additionally, elucidation of the temporal course and contribution of smooth muscle OGT signaling to lesion regression in diabetes is warranted." (PMID 37175604, 2023). "OGT adds UDP-GlcNAc to hydroxy groups in the serine/threonine residues of many proteins and is known to mediate many cellular processes such as immunity and cell cycle, and is also implicated in the pathological process of diseases such as diabetes and cancer." (PMID 37033243, 2023). "Future work will determine whether OGT-mediated O-GlcNAcylation drives VSMC fate transition during lesion pathogenesis in diabetes." (PMID 37175604, 2023). "However, PIP3 also recruits OGT to the cytomembrane through the strong interaction with the phosphoinositide-binding domain of OGT under diabetes or another insulin-insensitive state such as the prolonged postprandial response." (PMID 36295790, 2022). "Investigating the role of OGA and OGT in the presence of diabetes." (PMID 36353238, 2022).
diabetes (continued). "Moreover, the authors showed that OGT depletion in PTEC exacerbates fibronectin accumulation, tubular cell damage and lipid droplet accumulation associated with high-fat diet-induced diabetes." (PMID 36058931, 2022). "Moreover, OGT was revealed to participate in the regulation of nerve injury response in the neuropathy related to diabetes and aging." (PMID 34462420, 2021). "This suggests that miR-200a/200b mimics may play a therapeutic role by decreasing diabetes-induced endothelial inflammation through the downregulation of both OGT and ICAM-1." (PMID 29720943, 2018). "Increased OGT expression and protein O-GlcNAcylation showed pro-inflammatory effects in the HG-treated HAECs, representing one of the important mechanisms sustaining endothelial inflammation in diabetes." (PMID 29720943, 2018). "In summary, whilst OGT inhibitors currently lack specificity and selectivity, improvements in OGT inhibitors is necessary to be able to reduce protein O-GlcNAc levels and represents a potentially huge opportunity to reduce cancer or diabetes burden." (PMID 30697194, 2018). "We hypothesized that O-GlcNAc and OGT would physically associate with mSin3A/HDAC1/2 in the heart, and that this interaction would be altered by diabetes and exercise." (PMID 23835259, 2013). "In diabetes, hyperglycemia induces overactivity of the hexosylamine biosynthesis pathway (HBP), leading to increased synthesis of UDP-N-acetyl-d-glucosamine, a substrate that O-linked N-acetylglucosamine (GlcNAc) transferase (OGT) uses to O-GlcNAcylate the target protein." (PMID 34588426, 2021). "Furthermore, our findings that OGT‐eIF4E axis contributes to high glucose activating hepatoma cell stem‐like cell potential might provide a cue of the pathogenesis of HCC with diabetes." (PMID 30677218, 2019). "The catalytic activity of OGT is highly sensitive to the UDP-GlcNAc level, and as such, O-GlcNAcylation is elevated in response to diabetes." (PMID 38139429, 2023). "The authors also showed that diabetes affects the mitochondrial levels of OGA and OGT and their localization and activity." (PMID 30420836, 2018). "Disruptions in the cycling of O-GlcNAc mediated by O-GlcNAc transferase (OGT) and O-GlcNAcase (OGA), respectively, is a driving force for aberrant cell signaling in disease pathologies, such as diabetes, obesity, Alzheimer's disease, and cancer." (PMID 30237786, 2018). "A previous study suggests that OGT/HCF-1 complex is a glucose sensor because glucose availability modulates gluconeogenesis through OGT/HCF-1 complex, and that O-GlcNAc signaling serves as a nexus between nutrient flux or insulin resistance and diabetes." (PMID 27331873, 2016). "While our data suggests a putative crosstalk between YY1/SRF-related mechanisms and OGT-mediated VSMC de-differentiation, additional studies are warranted to elucidate the molecular pathways that link OGT to YY1 and SRF in regulation of VSMC phenotypic transformation in diabetes." (PMID 37175604, 2023). "Our current findings prompt us to speculate that YY1- and SRF-dependent pathways play a regulatory role in OGT-mediated SMC de-differentiation induced by hyperglycemia, promoting accelerated atherosclerotic lesion formation in diabetes." (PMID 37175604, 2023). "These mild phenotypes are distinct to that of mice lacking OGT in their β-cells, where they develop severe hyperglycemia and over diabetes in early adulthood in part by decreased β-cell mass and insulin secretion failure." (PMID 36387851, 2022). "Vitamin D might contribute in ameliorating diabetes complications not only by improving blood glucose and insulin levels, but also by suppressing AGER and OGT gene expression in the liver." (PMID 31231498, 2019). "Therefore, the primary objective of the current study was to determine whether smooth muscle OGT plays a direct role in the development of hyperglycemia-induced atherosclerosis and SMC de-differentiation in diabetes." (PMID 37175604, 2023).
diabetes (continued). "Mice lacking OGT in pancreatic β-cells develop diabetes and β-cell failure." (PMID 37107691, 2023). "Despite a strong correlation of increased O-GlcNAcylation during insulin resistance/diabetes, some studies indicate that reducing this protein modification (by inhibiting OGT or overexpressing OGA) in vitro is not sufficient to prevent insulin resistance in adipocytes." (PMID 37107691, 2023). "However, the fundamental contribution of OGT as a driver of atherosclerotic lesion formation in diabetes has not been previously explored." (PMID 37175604, 2023). "OGT preference for substrate is influenced by the levels of UDP-GlcNAc25, so activation of the HBP can shift the profile of proteins that are O-GlcNAcylated, and therefore it was not surprising to find that some were less represented in the samples from mothers with diabetes." (PMID 34667181, 2021). "Protein abundance of OGA and the OGT:OGA ratio was not altered by diabetes or at any age." (PMID 32153425, 2020).
hepatocellular carcinoma (36 papers, 2018 to 2026). A malignant tumor that arises from hepatocytes. "Studies suggest that OGT plays an oncogenic role in non-alcoholic fatty liver disease-associated hepatocellular carcinoma (NAFLD-HCC) through activating JNK/c-Jun/AP-1 cascade by increasing p-JNK, p-c-Jun protein expression and AP-1 activation." (PMID 35432358, 2022). "We found that KAT5 was O-GlcNAcylated by OGT in PCK1-deficient hepatoma cells, and O-GlcNAcylation of KAT5 enhanced its stability." (PMID 34650217, 2021). "For example, decreased O-GlcNAcylation caused by OGT inhibitor OSMI-1 enhances doxorubicin-induced apoptosis in hepatocellular carcinoma (HCC) cells." (PMID 37251080, 2023). "However, the underlying mechanisms by which OGT regulates hepatoma development remain largely unknown." (PMID 30677218, 2019). "Conversely, mTOR inhibitors in hepatocellular carcinoma decrease global O‐GlcNAcylation by promoting OGT degradation via ubiquitin–proteasome and selective autophagy pathways, establishing a negative feedback loop." (PMID 41540817, 2026). "O-GlcNAcylation, and the enzyme responsible for this modification, OGT, are both usually increased in tumors and promote many hallmarks of cancer including hepatocellular carcinoma (HCC)." (PMID 41550490, 2026). "A similar result has also been reported in NAFLD-related hepatocellular carcinoma with upregulated OGT, O-GlcNAcylation-induced NF-κB cascades, and activated endoplasmic reticulum stress." (PMID 36768465, 2023). "In another example, the ribosomal receptor for activated C-kinase 1 (RACK1), an important component of the 40S ribosome subunit, was identified to interact with OGT in hepatoma cells." (PMID 36291918, 2022). "In hepatoma HepG2 cells, mSin3A interacts with the OGT N-terminal TPR region and recruits it to the promoters for transcriptional repression." (PMID 36291918, 2022). "In our previous study, we observed elevated O-GlcNAcylation in liver cancer and found that overexpression of OGT facilitated hepatocellular carcinoma (HCC) tumorigenesis." (PMID 33863873, 2021). "Aberrant hyper-O-GlcNAcylation is reported to yield hepatocellular carcinoma (HCC) malignancy, but the underlying mechanisms of the OGT/OGA imbalance responsible for HCC tumorigenesis remain largely unknown." (PMID 34298689, 2021). "Together, OGT promotes hepatoma cell proliferation and stem‐like cell potential at least partly through stabilization of eIF4E expression." (PMID 30677218, 2019). "First, OGT knockdown attenuated not only the ability of proliferation but also stem‐like cell potential of hepatoma cell." (PMID 30677218, 2019). "In summary, we have described a novel role for the metabolic sensor OGT in the growth and stem‐like cell potential of hepatoma cells." (PMID 30677218, 2019). "Collectively, our findings indicate that OGT promotes the stem‐like cell potential of hepatoma cell through O‐GlcNAcylation of eIF4E." (PMID 30677218, 2019). "Here, we employed the lentiviral shRNA‐based system to knockdown OGT to analyse the contribution of OGT in hepatoma cell proliferation and stem‐like cell potential." (PMID 30677218, 2019). "OGT activated stem‐like cell potential in hepatoma cell partly through up‐regulation of eIF4E expression." (PMID 30677218, 2019). "CCK8 assay showed that the inhibitory effect of OGT knockdown on the proliferation of hepatoma cell was rescued by expression of exogenous eIF4E." (PMID 30677218, 2019). "OGT activated stem‐like cell potential in hepatoma through eukaryotic initiation factor 4E (eIF4E) which bound to stem‐related gene Sox2 5'‐untranslated region." (PMID 30677218, 2019). "We found that the level of total O‐GlcNAcylation or OGT protein was increased in hepatocellular carcinoma." (PMID 30677218, 2019). "To learn the pathophysiologic significance of O‐GlcNAcylation in hepatoma development, we first determined the level of O‐GlcNAcylation and OGT in human hepatocellular carcinoma and adjacent normal tissues." (PMID 30677218, 2019).